FAT1 (FAT atypical cadherin 1)
Diseases named in the same sentence as FAT1 in open-access papers (continued):
Sharing a sentence is not in itself a finding about the gene and the disease.
tumor (continued). "This study now serves to reconcile these differences wherein subtype-specific effects of FAT1 accommodate both oncogene and tumor suppressor functions." (PMID 40083689, 2025). "Upstream tumor suppressors, including MST1, LATS1/2, and FAT1/2/3/4, frequently undergo deletions or mutations, whereas downstream oncogenes such as YAP1, WWTR1, and TEAD1/2/3/4 are upregulated." (PMID 41256331, 2025). "Our study identifies a mechanism by which YAP/TAZ levels are kept low through FAT1/MIB2-mediated protein degradation and shows that tumor progression resulting from mutation of tumor suppressor FAT1 involves loss of MIB2-dependent degradation of YAP and TAZ." (PMID 40478800, 2025). "The function of FAT1 in human cancers varies depending on the type of cancer, as it can act as either an oncogene or a tumor suppressor." (PMID 40672387, 2025). "Our study revealed the role of FAT1 as a tumor suppressor and underscored its potential as a promising therapeutic target for HNSCC." (PMID 39781458, 2025). "In preclinical RCC models, the FAT1 protein functions as a tumor suppressor by acting as a cell-surface inhibitor of YAP1." (PMID 41465847, 2025). "In summary, Our identified FAT1 mutation-related risk signature shows potential for assessing LUAD clinical outcomes, tumor immunogenicity, and immunotherapy effectiveness, providing valuable insights for LUAD clinical practice." (PMID 40672387, 2025). "Building upon our in vitro findings that tumor-mimetic extracellular matrix stiffness suppresses FAT1 expression in LECs, we next characterized the expression pattern of FAT1 in lymphatic vessels during tumor progression in vivo." (PMID 41230499, 2025). "In contrast, knockout of FAT1 in HN12 and JHU029 cells, which harbor wild‐type FAT1, resulted in enhanced cell proliferation and increased colony formation, highlighting the tumor‐suppressive role of wild‐type FAT1 in HNSCC cells." (PMID 40407216, 2025). "Nonetheless, the broad range of FAT1 tumor expression compared to normal tissues presumably reflects the spectrum of FAT1 loss and overexpression." (PMID 40083689, 2025). "2D migration assays demonstrated consistent enhancement across different mechanical environments, with FAT1 knockdown mLECs showing improved motility on both matrices with physiological stiffness and tumor-mimetic stiffness." (PMID 41230499, 2025). "FAT1 has been proposed to be tumour suppressive and involved in various signalling pathways, including the CaMK2, WNT and Hippo signalling pathways." (PMID 39738653, 2024). "Taken together, we show that FAT1 loss in NSCLC attenuates HR and exacerbates CIN through two distinct downstream mechanisms, leading to increased tumour heterogeneity." (PMID 39738653, 2024). "By acting as a tumor suppressor, FAT1 helps prevent the uncontrolled growth and spread of cancer cells." (PMID 39169426, 2024). "For instance, fusions of oncogenic proteins TAZ, YAP1, and HIPK2 preserve their tumor-promoting function, while fusions of tumor suppressors, such as NF2, LATS1, FAT1, PTPN14, DCHS2, TAOK1, and TAOK3, results in loss of their function." (PMID 38499647, 2024). "We also demonstrated that dietary ω-3 PUFAs supplementation enhances the efficacy of immunotherapy in preclinical murine tumor models and that anti-PD-1 potently inhibits primary tumor growth in Fat-1 transgenic mice." (PMID 38330013, 2024). "Significant positive correlations with GPX4 (ferroptosis), ACSL4 (fatty acid metabolism), SOD2 (antioxidant), HIF1A (tumor growth and metastasis), FAT1 (fatty acid metabolism) and IREB2 (Iron-responsive element)." (PMID 38206305, 2024).
tumor (continued). "FAT4 (GA + PA vs. Sham + PA, GDA + PA vs. Sham + PA, and GDA + PA vs. Placebo + PA) and FAT1 (GA + PA vs. Sham + PA and GA + PA vs. Placebo + PA) were the top increased tumor suppressors based on FDR." (PMID 39409043, 2024). "The main tumor susceptibility genes in CBC3T-1 cells included BARD1, KDR, FAT1, HNF1A, BRCA2, FANCA, and BRCA1." (PMID 37966669, 2024). "Pathway enrichment analysis suggested the involvement of FAT1 in tumor development pathways, and its expression was closely associated with immune cell infiltration." (PMID 38453442, 2024). "Using the multiregional sequencing of the TRACERx study to time the occurrence of FAT1 alterations, we observed evidence of positive selection for tumour subclones with FAT1 alterations before WGD." (PMID 39738653, 2024). "FAT1 has been shown to negatively regulate YAP and TAZ in zebrafish and mammals, and loss of FAT1 function in tumor cells results in YAP/TAZ activation through incompletely understood mechanisms." (PMID 37031213, 2023). "FAT1 exhibited complexity in modulating tumorigenesis and acted as tumor promoter or suppressor depending on tumor types." (PMID 37633919, 2023). "Another tumor suppressor gene typically mutated in both OSCC and CSCC is FAT1 (FAT atypical cadherin), a member of the cadherin superfamily." (PMID 37370836, 2023). "These were commonly male patients with local tumours and mutations in VHL and wild-type FAT1 and STAG2." (PMID 37391505, 2023). "FAT1 regulates cell–cell contact and acts as a tumor suppressor or oncogene in a context-dependent manner." (PMID 37245006, 2023). "In OSCC, therapy targeting FAT1 successfully inhibited tumor progression and increased sensitivity to chemotherapy." (PMID 38293699, 2023). "We found that FAT1 was significantly increased in Z8-treated xenografts in addition to the retention of YAP1 in the cytoplasm of tumor cells and suppression of ALDH1A1." (PMID 37147285, 2023). "Loss-of-function mutations in FAT1 and NF2 can result in enhanced YAP/TAZ protein accumulation, nuclear translocation, and the activation of transcription, leading to tumor progression, metastasis, and therapy resistance." (PMID 37835395, 2023). "Gene expression was evaluated in treated and untreated tumor cells; it was observed that the treatments with EC (300 μM) induced higher expression of the anti-proliferative genes Cdh1, Mtss1, Pten, Bmrs, Fat1, Smad4, and Nrf2." (PMID 37687058, 2023). "Fat1 expression can inhibit cell proliferation, colony formation, and cell migration and invasion, whereas Fat1-knockout induces increases in migration and tumor invasion." (PMID 37687058, 2023). "Seven heterozygous protein-truncating mutations were found in tumor suppressor genes including RB1, FBXO11, FAT1, KMT2D, KMD6A, ACVR2A and ZFHX3." (PMID 36702998, 2023). "In HNSCC, FAT1 mutations induce EMT status, thereby promoting tumor occurrence, progression, invasiveness, and metastasis." (PMID 38293699, 2023). "One tumor was positive for HPV45 and had mutations in FAT1 and FAT2; the other was positive for HPV31 and had mutations at NOTCH1, MAPK1, and HIST1H2AK." (PMID 38058352, 2023). "There are indications that FAT4 homolog, protocadherin family FAT1 binds β-catenin in endothelial damage repair and human tumor cells." (PMID 37658376, 2023). "We performed enrichment analyses to identify the potential effects of FAT1 in tumor pathways, reverse regulation of cell differentiation, transcription factor binding, and epithelial cell development." (PMID 36517565, 2022). "Next, we studied the effect of FAT1 knockdown on the secretion of cytokines from tumor cells using multi-analyte ELISArray kit (Qiagen)." (PMID 35720420, 2022). "FAT1 is a Drosophila tumor suppressor, which has important functions in regulating the Wnt pathway and the Hippo pathway." (PMID 36741696, 2022). "FAT1 was expressed remarkably high in tumor tissues compared to normal tissues and in stage IV compared to stage I tumor tissues in the whole cohort (P < 0.01)." (PMID 35646625, 2022).
tumor (continued). "Tumor sites were significantly different between the FAT1‐LR and FAT1‐HR subgroups (oral cavity 44.47% vs. 67.47%; oropharynx 31.54% vs. 11.51%; P = 2.2e−16)." (PMID 34939311, 2022). "The FAT1 protein level also performed well in distinguishing tumor and normal tissues in HNSC and OSCC (AUC = 0.79 and 0.829)." (PMID 35646625, 2022). "The number of benign and malignant tumors per mouse was noted to increase in Fat1-cKO mice, suggesting that Fat1 acts as a tumor-suppressor gene in DMBA/TPA-induced skin SCCs." (PMID 35965328, 2022). "These genes have been associated with tumour suppression (BRCA1 and FAT1), DNA repair (POLE), morphogenesis (HOXD11), epigenetic regulation (WHSC1), lipid metabolism (PPARG) and red blood cell development (GATA1)." (PMID 36131292, 2022). "FAT1 gave a positive staining in 62.6% (67/107) tumor front samples, 55.1% (65/118) tumor center samples, and 0.3% (3/116) normal tissues." (PMID 35646625, 2022). "Our study unravels a novel function of FAT1 in the maintenance of immunosuppressive tumor microenvironment." (PMID 35720420, 2022). "The expression levels of FAT1 were evaluated independently at the tumor center and the invasion front, which was defined as the tumoral advancing edge." (PMID 35646625, 2022). "Through AUC, both FAT1 mRNA and protein levels performed well in distinguishing tumor and normal tissues (AUC = 0.78)." (PMID 35646625, 2022). "In contrast, FAT1-knockout tumor cells were significantly more sensitive to the SRC inhibitor dasatinib and SRC/Bcr-Abl inhibitor saracatinib and the CAMK2 inhibitor KN93 as compared to FAT1 wild-type cells." (PMID 35965328, 2022). "Like cell surface FAT1, circFAT1 has a dual-function, either inhibiting or promoting tumor progression in a cancer specific manner through sponging miRNAs and repressing their downstream pathways." (PMID 35965328, 2022). "Since FAT1 is downregulated in many types of cancer and plays a role in controlling cell proliferation and migration, it has been considered a tumor suppressor." (PMID 35965328, 2022). "FAT1 is an upstream YAP1 inhibitor that is mutated in nearly 30% of HNSCC, and FAT1 deletion has been proposed to contribute to a hybrid EMT state, tumor stemness, and metastasis." (PMID 36428690, 2022). "The proportion of FAT1-positive tumor front and tumor center samples was significantly higher than that in non-cancerous samples (P < 0.0001)." (PMID 35646625, 2022). "The results demonstrated that FAT1 was significantly correlated with one or more immune cell infiltration in all tumor types except CHOL." (PMID 36517565, 2022). "FAT1 also inhibits Wnt/β‐catenin signaling, which is important for cell proliferation and tumor growth." (PMID 34939311, 2022). "FAT1 has a tumor-suppressive role by interacting with β-catenin and suppressing its nuclear translocation." (PMID 36294681, 2022). "We have assessed the effect of modulated TGF-β secretion from FAT1-depleted tumor cells on in vitro migration and phenotype of monocyte-derived cell line." (PMID 35720420, 2022). "The present study aimed at gaining an insight into the role of FAT1 in the tumor genesis and development." (PMID 35646625, 2022). "Previous studies have revealed that FAT atypical cadherin 1 (FAT1) plays a tumor-suppressive or oncogenic role in a context-dependent manner in various cancers." (PMID 35646625, 2022). "Our transmigration results provide a functional relevance of the reduction found in immunosuppressive cytokines in response to FAT1 knockdown in tumor cells." (PMID 35720420, 2022). "FAT1 has been described as having both tumor suppressive and oncogenic roles, depending on the context." (PMID 34580376, 2021). "The human FAT1 regulates cell growth, migration, and polarization with a dual role as tumor suppressor and oncogene." (PMID 33527763, 2021).
tumor (continued). "Of these, we found that heterozygous missense mutations in four genes—FAT4, FAT1, FAT3, and ERCC2—were predicted to be deleterious and also detected by tumor RNA sequence data, indicating that the mutant alleles were expressed in the tumor." (PMID 33733072, 2021). "Analysis of the COSMIC database indicated that FAT1 is located at a gene deletion peak in tumor samples, further suggesting a tumor suppressor role for FAT1." (PMID 34150758, 2021). "To mechanistically understand the interaction of GPC3 and FAT1 in promoting HCC cell migration, we analyzed the regulation pattern of GPC3 and FAT1 on the expression of tumor metastasis-related genes under hypoxic conditions." (PMID 33420124, 2021). "This study also showed that FAT1 exerted tumour suppressor activity specifically in FLT3‐ITD‐positive AML, perhaps providing a partial explanation for the lack of prognostic impact of FLT3‐ITD in this subpopulation." (PMID 34101344, 2021). "Inactivating mutations in FAT1 (n=3) and CDKN2A (n=3) were exclusively found in HPV-negative tumours." (PMID 34631566, 2021). "WNT signaling activation in HN tumor subsites has been associated with genetic alterations in AJUBA, FAT1 and NOTCH1." (PMID 34208581, 2021). "The outcome of next-generation sequencing showed a low tumor mutational burden (11.5 mut/Mb), and mutations in genes F-box and WD repeat domain containing 7 (FBXW7), PKHD1, and FAT atypical cadherin 1 (FAT1)." (PMID 34367140, 2021). "FAT1, which is frequently mutated in chronic lymphocytic leukemia (CLL) and can act as a tumor suppressor through inhibiting Wnt signaling, also overlaps with an MRR in K562." (PMID 33514712, 2021). "There are mutated tumor suppressor genes in all (nine/nine) tumor portions, such as EP300 and PTEN in GB01, NCOR2 in GB02, and FAT1 in GB03." (PMID 33922652, 2021). "Nevertheless, our germline analysis identified four genes with known functions likely to contribute to tumor progression and potentially drug response: FAT1 and FAT3, FAT4, and ERCC2, modeled by targeting kug, ft, and xpd, respectively." (PMID 33733072, 2021). "Among them, FAT1 is a transmembrane protein which plays an important role in the regulation of cell adhesion and growth, migration, actin dynamics and orientation in tumor progression." (PMID 34712552, 2021). "FAT1, which like CDC73 functions as a tumour suppressor, was found associated with CDC73 in independent AP-MS experiments in 293T and MDA-MB-231 cells and we thus focused on this interaction for this study." (PMID 34424918, 2021). "There are both suppressor genes and tumor oncogenes mutated in all nine/nine parts of the tumor, such as EP300 and NCOR2 (NOTCH), PTEN (PI3K), EGFR (RTK-RAS) and FAT1 (Hippo)." (PMID 33922652, 2021). "Cases with mutations in KEAP1 and FAT1 tended to have higher TMB and neoantigen loads but a lower expression of immune-related genes and tumor-infiltrating CD8+ cells than cases with wild-type genes." (PMID 33808631, 2021). "It is also pertinent to point out that previous literature has discussed the role of FAT1 in human cancers in two contexts- that of an oncogene as well as a tumor suppressor." (PMID 33878524, 2021). "With this purpose, we evaluated the proportion of cases of each tumor subsite carrying potential driver mutations and/or deep deletions in AJUBA, FAT1 and NOTCH1 in TCGA datasets." (PMID 34208581, 2021). "Knockdown of FAT1 leads to increased proliferation rate suggesting potential tumor suppressor function." (PMID 32974170, 2020). "Two tumors carried missense mutations predicted to be damaging by SIFT and PolyPhen2 in the tumor-suppressor gene FAT1." (PMID 33384420, 2020). "FAT1 is a well-studied tumor suppressor that plays a vital role in cell growth control and mitochondria function." (PMID 33113782, 2020).